CD4 (CD4 molecule)
Diseases named in the same sentence as CD4 in open-access papers (continued):
Sharing a sentence is not in itself a finding about the gene and the disease.
rheumatoid arthritis (continued). "This revealed an enrichment of rheumatoid arthritis and type 1 diabetes variants in CD4+ T cell subsets, particularly in regulatory T cells." (PMID 32477401, 2020). "Rheumatoid arthritis is associated with premature senescence of T-lymphocytes, and the accumulation of senescent CD4+CD28− T-cells has been linked with disease severity." (PMID 29472917, 2018). "Several studies in patients with inflammatory disorders such as rheumatoid arthritis have demonstrated that expansion of CD4+CD28null T cells is independently associated with increased incidence of CVD and cardiovascular mortality." (PMID 30157919, 2018). "For example, such analyses have implicated dysregulation of autophagy in Crohn’s disease, the pathogenic role of CD4+ effector memory T-cells in rheumatoid arthritis, and an overrepresentation of transcription factors in systemic lupus erythematosus." (PMID 29059182, 2017). "The SKG mouse expresses a hypomorphic mutant allele of ZAP70, which, upon exposure to fungal Ags, predisposes the mice to a CD4+ T cell–mediated autoimmune arthritis that closely resembles rheumatoid arthritis in humans." (PMID 27288531, 2016). "CD4 + CD28null cell expansions in turn have been associated with an increased risk of CVD in patients with CKD as well as rheumatoid arthritis." (PMID 27450392, 2016). "Glucose-6-phosphate isomerase (GPI)-induced arthritis is a closer model of human rheumatoid arthritis based on its association with CD4+ T cells and cytokines such as TNF-α and IL-6 than CIA." (PMID 23251456, 2012). "An ATM deficiency has been described in CD4+ T cells from rheumatoid arthritis (RA) patients, associated with premature immunosenescence." (PMID 23092393, 2012). "Methotrexate therapy is associated with depletion of all CD4+ T cell subsets, including Tregs, and also with the development of rheumatoid nodules following improvement of arthritis, as has been reported in previous studies." (PMID 22028728, 2012). "Inhibition of mitochondrial apoptotic cascade in CD4+CD28− T cells isolated from patients with rheumatoid arthritis has been shown to be the underlying molecular mechanism which gives rise to expansion and accumulation of CD4+CD28− T cells in these patients." (PMID 19779562, 2009). "Among them, Jacek M. Witkowski (Medical University of Gdansk) suggested that rheumatoid arthritis (RA) is associated with accelerated ageing of CD4+ T cells." (PMID 16504129, 2006). "α/β-hydrolase domain-containing protein 11 (ABHD11) is a mitochondrial hydrolase that maintains the catalytic function of α-ketoglutarate dehydrogenase (α-KGDH), and its expression in CD4+ T cells has been linked to remission status in rheumatoid arthritis (RA)." (PMID 40166327, 2025). "Finally, we postulate the clinical role of survivin-BRG1/SWI complex axis in pathogenic CD4+ cells abundant in synovia of patients with rheumatoid arthritis, and the ability of anti-rheumatic drugs to modulate the DNA damage response." (PMID 39261837, 2024). "Interestingly, CD28+ CD27- TEMRA and EM CD4+ T cells expressing Th1- and cytotoxicity-associated genes have also been described to be increased and associated with higher damage in rheumatoid arthritis patients." (PMID 35185762, 2022). "PD-1high MP CD4 T cells have recently been implicated in rheumatoid arthritis pathogenesis, and we have now found that Egr2 expression is reduced in PD-1high MP CD4 T cells from patients with active rheumatoid arthritis compared with healthy controls." (PMID 32709717, 2020). "IL-23 is involved in the proliferation of CD4+ Th17 cells to produce IL-17 and along with IL-17, associated with several autoimmune and inflammatory disorders such as psoriasis, psoriatic/rheumatoid arthritis, multiple sclerosis, Crohn's disease, uveitis, and inflammatory bowel disease." (PMID 32671018, 2020).
rheumatoid arthritis (continued). "Furthermore, our data are in agreement with several published studies reporting associations in other patient groups such as rheumatoid arthritis and chronic kidney disease, between CD4+CD28null T cells and markers of atherosclerotic damage." (PMID 30157919, 2018). "IL-17-producing CD4+ T helper cells (Th17) are important for pathogen clearance and tissue inflammation and are considered as a hallmark cell in a number of autoimmune diseases including rheumatoid arthritis (RA)." (PMID 28674533, 2017). "Similarly, microRNAs associated with TILs and CD4+ cells were enriched within the pathway termed, ‘Role of Macrophage, Fibroblasts, and Endothelial Cells in Rheumatoid Arthritis’." (PMID 28145100, 2017). "Dysfunctional CD46 signalling might also be implicated in the pathogenesis of rheumatoid arthritis (RA), where CD4+ T cells have a defect in the shutdown of IFNγ production following CD46 co-stimulation." (PMID 27739531, 2016). "Therefore, in a cross-sectional study, we investigated the occurrence of CD4+CD161+ T-cells in seropositive arthralgia patients who are at risk for developing rheumatoid arthritis and in newly diagnosed rheumatoid arthritis patients." (PMID 24223933, 2013). "Finally, we identified 146 likely causal genes for rheumatoid arthritis, including CD4, FGFR1, and KDR, which have been reported as high risk factors by recent studies." (PMID 20727150, 2010). "In addition, rheumatoid arthritis (RA) is caused mainly by CD4+ memory T cell accumulation in the inflamed synovium." (PMID 19787093, 2008). "CD4+ T cell autoreactivity against citrullinated (cit) self-epitopes presented by HLA-DRB1 is associated with rheumatoid arthritis (RA) pathogenesis." (PMID 40466907, 2025). "For example, risk variants for rheumatoid arthritis (RA) are enriched in regulatory elements specific for CD4 T cells, and studies in patients and mice have shown the relevance of these cells in the pathogenesis of this disease." (PMID 39197446, 2024). "This study was designed to assess the role of APC-mediated OX40L expression in the context of the development of rheumatoid arthritis (RA)-associated CD4+ T cell subsets." (PMID 36291190, 2022). "In addition, reduced telomere activity or telomere shortening in CD4+ T cells and/or leukocytes have been associated with age-related diseases like cardiovascular disease and immune-mediated diseases such as rheumatoid arthritis, type I diabetes mellitus and systemic lupus erythematosus." (PMID 35321714, 2022). "A higher frequency of CD4+ TSCM cells is shown to cause disease severity in rheumatoid arthritis (RA) patients." (PMID 36169248, 2022). "However, studies of CD4+ T cells in rheumatoid arthritis patients demonstrated that differentiation to pathogenic Th17 cells was dependent on increased ROS production, which could be inhibited by Mito-Tempo." (PMID 34072441, 2021). "Here we studied the association of CD146 expression and CD4+ IL-17+ activated memory T cells psoriatic arthritis (PsA), rheumatoid arthritis (RA) and osteoarthritis (OA) patients’ blood and synovial fluid (SF)." (PMID 34491483, 2021). "The majority of CD4+ T helper (Th) cells found in the synovial fluid (SF) of patients with rheumatoid arthritis (RA) express CXCR3, a receptor associated with Th1 cells." (PMID 33066816, 2020). "Further, CD4+ T cell involvement in Rheumatoid arthritis (RA) has been inferred from linkage to HLA-DR alleles and the presence of activated CD4+ T cells in inflamed joints." (PMID 27181093, 2016). "Rheumatoid arthritis (RA) is an autoimmune destructive arthritis associated with CD4+ T cell-mediated immunity." (PMID 26245356, 2015). "Impaired homeostasis and function of the immune system (especially of the CD4+ lymphocytes as the hub immune cells) underlies or at least participates in the pathology of Alzheimer's disease (AD) and of rheumatoid arthritis (RA)." (PMID 17683521, 2007).
rheumatoid arthritis (continued). "In rheumatoid arthritis, decreased EZH2 expression in circulating CD4+ T cells has been linked to impaired Treg differentiation." (PMID 41518566, 2026). "It explored how DNase induces indoleamine 2,3-dioxygenase (IDO) expression, regulates CD4+ T cells and reduces inflammation and tissue damage in a mouse rheumatoid arthritis (RA) model." (PMID 40988998, 2025). "The rheumatoid arthritis (RA) milieu polarizes CD4+ T cells to the pro-inflammatory T helper (Th) 17 phenotype with increased secretion of IL-17 and IL-22." (PMID 40852730, 2025). "Another study in the United States demonstrated that HLA-DRB1×04 contributes to excessive telomere reduction in CD4+T-cells, promoting senescence and accumulation of autoreactive T cells in patients with rheumatoid arthritis." (PMID 40907117, 2025). "In this issue of the JCI, McCarthy and colleagues used the SKG mouse model of rheumatoid arthritis to characterize the role of Sag activity in inflammatory arthritis by profiling arthritogenic naive CD4+ T cells." (PMID 39817448, 2025). "Tregs, a group of CD4+ immunosuppressive cells, maintain immune homeostasis and suppress the overactivated autoimmune response to reduce the severity of rheumatoid arthritis." (PMID 40469311, 2025). "In fact, 5-LOX has been shown to drive the pyroptosis of CD4+ T cells and tissue inflammation in rheumatoid arthritis." (PMID 40565171, 2025). "Downregulation of ZNF334 expression has been reported in various cancer tissues and in the CD4 + T cells of patients with rheumatoid arthritis." (PMID 41168503, 2025). "We explored this possibility initially in two autoimmune patient cohorts, isolating CD4+ T cells from rheumatoid arthritis (RA) and type 1 diabetes (T1D) patients and activating them in the presence and absence of ML-226 ex vivo." (PMID 40166327, 2025). "Previous studies described reduced ZNF334 transcription levels in cancer tissues and in CD4 + T cells of rheumatoid arthritis." (PMID 41168503, 2025). "In rheumatoid arthritis, B cells give their antigens to CD4+ T helper cells, categorized as follicular helper cells (Tfh) and peripheral helper cells (Tph)." (PMID 41127878, 2025). "In the RA data set, there was a slight increase in the infiltration of naïve B cells, CD8 + T cells, activated CD4 + memory T cells, regulatory T cells (Tregs), and M0 macrophages in rheumatoid arthritis patients." (PMID 39987090, 2025). "Using cytomegalovirus (CMV) and rheumatoid arthritis (RA) as models of chronic immune activation, we performed high‐dimensional mass cytometry and functional assays to define their impact on CD4+ T cells." (PMID 41235706, 2025). "For example, anti-CD4 antibodies have been tested in diseases like rheumatoid arthritis (RA) and multiple sclerosis (MS) to deplete activated CD4+ T cells, although challenges such as generalized immune suppression remain." (PMID 40006751, 2025). "CD4+ T cells play critical roles in autoimmune and inflammatory disorders, such as inflammatory bowel disease, type 1 diabetes, Crohn’s disease, and rheumatoid arthritis." (PMID 38308274, 2024). "We provide an application case by examining three Spike protein-derived immunodominant CD4+ T-cell epitopes restricted by HLA-DRB1*04:01, an allele strongly associated with susceptibility to rheumatoid arthritis (RA)." (PMID 38840924, 2024). "First, in patients with rheumatoid arthritis, the CD4 protein on helper T lymphocytes is activated, which then stimulates monocytes, macrophages, and fibroblast-like synoviocytes." (PMID 39085865, 2024). "In RA, adaptive immunity, dominated by CD4+ T cells, plays an important role in initiating and maintaining the autoimmune response characteristic of rheumatoid arthritis." (PMID 38475833, 2024). "Our observation was corroborated by colocalization of a rheumatoid arthritis GWAS signal overlapping the enhancer with a TRAF1 eQTL signal in CD4+ T cells." (PMID 38308274, 2024).
rheumatoid arthritis (continued). "In this study, we explored the role of BvCR in DNA damage response of autoimmune CD4+ cells in rheumatoid arthritis (RA)." (PMID 39261837, 2024). "In rheumatoid arthritis (RA), related types of GWAS analyses conversely identified genes and pathways pinpointing CD4+ effector memory T (TEM) cells as important for pathogenesis." (PMID 39596040, 2024). "CD8+ T-lymphocytes express β2-ARs in greater quantities than CD4+ cells, and these expressions are differentially regulated in both healthy and rheumatoid arthritis (RA) patients." (PMID 38476949, 2024). "In the early stages of ACPA-positive rheumatoid arthritis, a lot of CD4+ T cells and macrophages enter the synovium." (PMID 39530095, 2024). "Morbidly obese hASCs inhibited the proliferation of CD3 T cells, derived from rheumatoid arthritis (RA) patients, in a dose-dependent fashion, however, they promoted that of CD4+ FOXP3+ T cells." (PMID 37462786, 2023). "A study investigating rheumatoid arthritis found that memory Tregs (CD4+CD45RO+CD25+CD127low) can acquire the ability to produce pro-inflammatory cytokines, including not only IFN-γ and IL17, but also TNF, in response to inflammatory stimuli." (PMID 37047033, 2023). "The imbalance of CD4+T cell subsets in CIA mice plays a critical role in the pathogenesis of rheumatoid arthritis." (PMID 37570855, 2023). "CD4+ CTLs have been shown to exacerbate or be involved in multiple autoimmune diseases, including multiple sclerosis (MS) and rheumatoid arthritis (RA)." (PMID 37122720, 2023). "Research has shown that low expression of CD4+CD25+ regulatory T cells (Tregs) in patients with rheumatoid arthritis suggests that immune suppression mediated by CD25+ Tregs is an important mechanism in the development of rheumatoid arthritis." (PMID 37731506, 2023). "CD4+ T cells are critically involved in the pathogenesis of Rheumatoid Arthritis; an autoimmune disorder characterized by joint inflammation and bone degeneration." (PMID 37809066, 2023). "Multi-omic data was used to construct genome-scale metabolic models of CD4+ T cells to show perturbation in rheumatoid arthritis, multiple sclerosis, and primary biliary cholangitis." (PMID 38138860, 2023). "In models of rheumatoid arthritis, glycolysis‐mediated lactate produced by host tissues accumulated in inflamed synovial fluid and incited greater IL‐17 production upon uptake into CD4+ T cells, exacerbating joint destruction." (PMID 36354099, 2022). "Senescent Foxp3+CD4+CD28− T lymphocytes have been identified in patients with rheumatoid arthritis, which downregulate CD25 while showing increased expression levels of TNF-α and IL-17A in addition to decreased suppressive capacity." (PMID 35269683, 2022). "Even though rituximab’s main target is CD20+ B cells, it was documented to induce a substantial CD4 T cells depletion in a subset of patients with rheumatoid arthritis, which likely contributed to its clinical efficacy." (PMID 36209215, 2022). "Circulating CD4+ T helper (Th) cell responses of severe acute respiratory syndrome coronavirus 2 (SARS-CoV-2) mRNA vaccinated SARS-CoV-2 experienced rheumatoid arthritis using methotrexate (RA-MTX) and multiple sclerosis using ocrelizumab (MS-OCR) patients." (PMID 35838348, 2022). "Survivin expressing CD4+T cells were identified by flow cytometry of the mononuclear leukocytes from the peripheral blood of 22 (16 female, 6 male) patients with rheumatoid arthritis (RA)." (PMID 36425763, 2022). "Enrichment of CD4+CD28− T cells in the inflamed tissue provided the first clue that patients with rheumatoid arthritis have premature immune aging." (PMID 35141865, 2022). "CD4+CD25+Foxp3+ regulatory T (Treg) cell-mediated immunosuppression is an essential mechanism of rheumatoid arthritis (RA)." (PMID 36064312, 2022). "Similarly, in rheumatoid arthritis (RA), an osteo-autoimmune disease caused by cartilage depletion in inflamed joints, osteoclast stimulation of bone resorption is CD4+ cell-mediated." (PMID 35881303, 2022).
rheumatoid arthritis (continued). "A recent study focusing on Eomes+CD4+ CTLs has expanded and documented their roles in anti-tumor immunity and pathological responses in inflamed conditions such as rheumatoid arthritis and multiple sclerosis." (PMID 36091071, 2022). "Overexpression of TIGIT suppressed CD4+ T cells and ameliorated the severity of rheumatoid arthritis in mouse models." (PMID 35844584, 2022). "Our findings on hydroxychloroquine's unfavorable effects on CD4 cell production are similar to those advocated for its usage in other diseases (e.g., rheumatoid arthritis)." (PMID 35911334, 2022). "Studies have shown that GPSM2 expression decreases CD4 T+ cells in rheumatoid arthritis patients and can act as a promoter of regular T cell migration in healthy individuals." (PMID 36186420, 2022). "For example, compared with the absolute number of CD4+Treg cells in peripheral blood of healthy people, the absolute number of CD4+Treg cells in new-onset rheumatoid arthritis patients was significantly lower." (PMID 36497177, 2022). "Sodium lactate or lactic acid inhibit the proliferation of murine CD4 T cells and Haas and colleagues have demonstrated that lactic acid treatment impairs the migration of human CD4 T cells in rheumatoid arthritis." (PMID 35682650, 2022). "In particular, adaptive immunity dominated by CD4+ T cells plays an important role in initiating and maintaining the characteristics of the autoimmune response in rheumatoid arthritis." (PMID 36217542, 2022). "has shown that rheumatoid arthritis patients with a good prognosis have higher PLT-binding CD4 T cells than patients with worse prognosis and healthy controls, suggesting that PLT-binding helps prevent the flared immune reaction against self." (PMID 35603202, 2022). "In fact, aged naive CD4+ T cells from rheumatoid arthritis patients divide faster than those in age-matched healthy controls, even though they showed accelerated aging." (PMID 35386693, 2022). "SOX-4–mediated CXCL13 production by CD4 T cells is involved in the formation of ectopic lymphoid-like structures (TLSs) in rheumatoid arthritis." (PMID 33332284, 2021). "CD4+ T cells are critical for the development of interstitial pneumonitis followed by rheumatoid arthritis." (PMID 33959573, 2021). "It has been reported that NLRP3 knockdown by using siRNA in CD4 T cells isolated from rheumatoid arthritis (RA) patients suppressed Th17 differentiation." (PMID 34234669, 2021). "More recently, a novel CD4 T peripheral helper (Tph) cell population, PD-1hiCXCR5-CD4+, was found to be expanded in rheumatoid arthritis." (PMID 33936082, 2021). "In fact, finding an increased number of prematurely senescent CD4+CD28- T lymphocytes has become relatively common in rheumatoid arthritis, juvenile idiopathic arthritis, ankylosing spondylitis, osteopenia, osteoporosis, and osteomyelitis." (PMID 34341698, 2021). "In order to identify how the synovial microenvironment impinges on CD4+ T cells pathogenic functions in Rheumatoid Arthritis (RA), Amaral-Silva examined RA patient blood and synovial fluif and identified the presence of a TLR4+ follicular helper T (Tfh) cell-like population." (PMID 34580414, 2021). "Aberrant expression of IL-1RI and IL-RII in synovial CD4 T cells in patients with rheumatoid arthritis (RA)." (PMID 33507149, 2021). "Here, we develop genome-scale models of naïve, Th1, Th2, and Th17 CD4+ T-cell subtypes to map metabolic perturbations in rheumatoid arthritis, multiple sclerosis, and primary biliary cholangitis." (PMID 33483502, 2021). "For example, CD4+ cells have a central control in autoimmune disorders such as rheumatoid arthritis and are present more predominantly than CD8ɑ+ cells." (PMID 34045665, 2021). "For instance, a reduction in CD4+ T cells expressing TIGIT has also been observed in rheumatoid arthritis and psoriasis." (PMID 33995373, 2021).